Y_RNA (Y RNA )
Gene: Miscellaneous RNA gene on chromosome 1 (39,881,566 to 39,881,678, reverse strand). Ensembl gene ENSG00000202222.
Homologues: Orthologues: chimpanzee Y_RNA (100% identical), macaque Y_RNA (95% identical), guinea pig Y_RNA (84% identical). Paralogues in human: RNY1 (87% identical), Y_RNA (87% identical), Y_RNA (86% identical), Y_RNA (85% identical), RNY1P11 (84% identical), Y_RNA (84% identical), Y_RNA (83% identical), Y_RNA (82% identical), RNY1P8 (81% identical), Y_RNA (81% identical), RNY1P10 (81% identical), RNY1P5 (81% identical), and 96 more.